EGFR (epidermal growth factor receptor)
Diseases named in the same sentence as EGFR in open-access papers (continued):
Sharing a sentence is not in itself a finding about the gene and the disease.
tumor (continued). "Other preclinical and clinical studies showed a correlation of tumor response to EGFR inhibition in NSCLC to early reduction in SUV as assessed by FDG-PET/CT, particularly in tumors with EGFR mutations." (PMID 25081631, 2014). "Some markers, like HER2 and EGFR are expressed at higher levels in cancer cells as compared with normal cells in certain tumor types, but it remains questionable if a different level of expression is, by itself, diagnostic of the tumor cell nature." (PMID 25527469, 2014). "We found that MVP expression is almost constitutively activated during malignant transformation in tumours of astrocytic origin and supports EGFR/PI3K signalling pathway activation leading to enhanced starvation resistance and migration/invasion potential." (PMID 24243798, 2013). "IgA2 EGFR also mediated efficient anti-tumour activity in a lung metastasis model using B16F10-EGFR cells in immunocompetent mice." (PMID 23918228, 2013). "The anti-tumour activity of IgA2 EGFR was dependent on FcαRI in both lung models and in the Ba/F3-EGFR peritoneal model, demonstrating a dominant role for ADCC." (PMID 23918228, 2013). "Met signaling pathway induces invasive tumor growth and shares many components and mechanisms with EGFR signaling pathway." (PMID 24287743, 2013). "The mAbs cetuximab and fully humanized panitumumab are specific for the extracellular domain of EGFR and display anti-tumor activity in patients." (PMID 24349829, 2013). "Underlining this notion, γ-secretase has been reported to function as a tumor suppressor in epithelia via Notch signaling as well as via epidermal growth factor receptor and β-catenin." (PMID 24223915, 2013). "In vitro experiments have confirmed that blocking EGFR activation inhibited the proliferation of certain types of tumor cells." (PMID 24273605, 2013). "Secondary T790M mutation seems to be acquired by the selection of pre-existing populations of T790M-harboring cells among the total tumor cells during the period of treatment with EGFR-TKI." (PMID 24369725, 2013). "In vitro incubation of IgA EGFR-opsonized A431 cells with complement active mouse blood resulted in deposition of iC3b on tumour cells, albeit less than what is induced by cetuximab." (PMID 23918228, 2013). "Subsequent TaqMan analysis of tumour-specific messages showed that tumour EVs were enriched in devices coated with an EGFR antibody." (PMID 26082317, 2013). "A preclinical study suggested a synergistic effect on tumor growth inhibition when combined with either a chemotherapeutic agent or an anti-EGFR antibody." (PMID 23921573, 2013). "Activation of STAT5 has also been shown to contribute to tumor growth and resistance to cisplatin and EGFR-inhibition in HNSCC cell lines." (PMID 24192080, 2013). "Because they displayed the highest EGFR signaling activation, three tumor lines (TCG2, TCG3, and TCG4) were selected to evaluate the antitumor effect of gefitinib combined with irradiation, as compared to GEF alone and ionizing radiation alone." (PMID 23874590, 2013). "Different lines of experimental evidences point to the existence of EGFR addiction in tumor initiating cells derived from neural tissue." (PMID 23637683, 2013). "As EGFR hyperactivity is considered critical in the initiation and progression of epithelial derived tumours, EGFR tyrosine kinase inhibitors have therapeutic potential as chemopreventative agents for gastrointestinal neoplasia." (PMID 25437333, 2013). "The mean tumor reduction using the administration of CIK cells directed by the EGFR/CD3 BsAb was higher than those of the other groups (P<0.05)." (PMID 23833649, 2013). "Hep3B xenografts, which express high levels of EGFR, were clearly visualized starting at 1 h p.i., with the excellent tumor imaging quality at later time points (4 and 24 h p.i.)." (PMID 23710458, 2013). "Whatever the tumor line, phospho-EGFR was always significantly overexpressed as compared to the non-tumor brain tissue." (PMID 23874590, 2013).
tumor (continued). "For selective targeting to tumor cells, we fused the epidermal growth factor receptor (EGFR) peptide ligand transforming growth factor α (TGFα) to human pre-pro-GrB." (PMID 23573299, 2013). "The pooled RR was 3.80 (95% CI 2.49–5.79), indicating that EGFR TKIs have a significant tumor shrinking effect after induction with chemotherapy." (PMID 23555654, 2013). "Tumour cell lysis by both cetuximab and IgA EGFR was already detectable after 120 min (unpublished data)." (PMID 23918228, 2013). "For example, in the presence of EGFR inhibitors, such as gefitinib, a subset of tumor cells with high Met expression (i.e., with Met gene amplification) can escape EGFR inhibition." (PMID 24287743, 2013). "For all these reasons, the maintenance of gefitinib after tumor progression emerges as an important new therapeutic strategy to inhibit EGFR-mediated aggressive behaviour in NSCLC with MET amplification." (PMID 24167634, 2013). "We report that although EGFR → ERK pathway inhibition initially attenuates tumor progression and induces tumor regression, it is uniformly limited by an acquired drug resistance, and subsequent failure to sustain either tumor regression or stability." (PMID 23342981, 2013). "Tumor microdissection yielded 2,699 foci, including 1,238 foci from wild-type EGFR (group-W) and 1,431 group-M cases." (PMID 23418425, 2013). "Retrospective studies in which long- term archived paraffin embedded tissue was used to determine EGFR status showed a low proportion of adequate tumor tissue available." (PMID 23922984, 2013). "In HCC, there is increasing evidence demonstrating a correlation between EGFR overexpression and tumor aggressiveness, metastasis formation, therapy resistance, and poor prognosis of this disease." (PMID 23710458, 2013). "This is in line with a recent report showing that monocytes/macrophages can mediate significant tumour cell killing with IgA EGFR." (PMID 23918228, 2013). "Several other glyco-engineered antibodies targeting a variety of different tumor associated antigens like CD19, CD20, EGFR, and GD2 are currently investigated in early clinical studies." (PMID 23543707, 2013). "EGFR mediates signals that stimulate proliferation, migration, and metastasis in many tumour types, and its signal transduction is regulated by stimulatory and inhibitory inputs." (PMID 24314030, 2013). "In conclusion, the present study demonstrated that the EGFR tyrosine kinase inhibitor, erlotinib, combined with ionizing radiation induced cell cycle arrest at the G2/M phase and reduced tumor volume in a xenograft model." (PMID 24137317, 2013). "Several recent studies comparing EGFR mutation status in primary tumor and local lymph node metastases have suggested a possibility of significant discrepancies between the sites because of tumor heterogeneity, which may be a cause of resistance to treatment with EGFR tyrosine kinase inhibitors." (PMID 24340058, 2013). "As the occurrence of EGFR on the tumor cells is critical for EGF-SubA toxin delivery, its presence was confirmed on the surface of all selected cell lines." (PMID 23887632, 2013). "Key molecular changes like mutation in the epidermal growth factor receptor (EGFR) are involved in cell proliferation and cell survival in the neoplasms." (PMID 23620765, 2013). "In contrast, serum spheroid cultures seem to be the best conditions to preserve tumor cells with EGFR amplification as also observed previously." (PMID 24349039, 2013). "Resv has shown to directly bind EGFR in cytoplasmic membrane of tumour cells thus rapidly inhibiting its over-activation." (PMID 23527233, 2013). "Qayum and colleagues showed that inhibition of EGFR- Ras-PI3 K-Akt signaling at multiple points in this pathway led to vascular normalization accompanied by improved tumor oxygenation and perfusion." (PMID 23509762, 2013). "Greater growth inhibition of tumors was seen in tumor induced by subclones with high EGFR expression compared with those with low EGFR expression." (PMID 23824671, 2013).
tumor (continued). "PLC/PRF/5 xenografts, which express low levels of EGFR, also showed distinct tumor accumulation, with clear tumor imaging and high tumor-to-background ratios at 4 and 24 h p.i.." (PMID 23710458, 2013). "The EGFR/CD3 BsAb directs CIK cells to tumor cells by connecting CD3 on effector cells with EGFR on tumor cells." (PMID 23833649, 2013). "Tumor volume was significantly lesser in the cetuximab-treated groups that were engrafted with cells expressing high levels of EGFR." (PMID 23824671, 2013). "There are several implications from these results, specifically when considering EGFR related mechanisms of oncogenesis and tumor biology, or pathologies wherein PKC and PLD activities are increased." (PMID 24244711, 2013). "In order to proof the functionality of the expressed sdAbs, we radiolabeled the purified proteins with 99mTc and investigated specific binding to human EGFR-expressing tumor cells." (PMID 24161153, 2013). "This clearly demonstrated a preferential accumulation of the EGFR-immunoliposomes within the tumor tissue." (PMID 24175095, 2013). "A number of tumor-associated or epithelial-specific genes are used in the detection of CTCs of different types of cancer, including CK, Her2, CEA, MUC1, EpCAM, EGFR, hTERT, survivin, c-met, FN1 and several other mRNA markers." (PMID 23599802, 2013). "EGFR activation has been shown to play a key role in tumor cell proliferation, apoptosis, tumor-induced angiogenesis, metastasis, and DNA damage repair after cytotoxic insults." (PMID 24252457, 2013). "Based on the immunohistochemical staining, subcutaneous transplantation tumor of A431, positive control, showed 3+ EGFR expressions, whereas high WiDR and SW480 had 2+ EGFR expressions." (PMID 23824671, 2013). "The results suggested that the EGFR/CD3 BsAb and EGFR McAb were able to direct CD3 positive CIK cells to tumor cells and the ability of the EGFR/CD3 BsAb to target CIK cells to tumor cells was higher than that of EGFR McAb." (PMID 23833649, 2013). "The ErbB family member EGFR is over-expressed and shows hyperactivity in many tumor types, including PDAC, and is recognized as an important molecular target for therapy." (PMID 24025152, 2013). "Patterns of tumor ploidy and allelic imbalances between mutational groups were evaluated by GAP analysis of 141 tumors (n=43 EGFR-mutated, 39 KRAS-mutated, and 59 EGFRwt/KRASwt) profiled by SNP microarrays." (PMID 24205279, 2013). "Similar to gefitinib and erlotinib, icotinib inhibited growth of human tumor cell lines that overexpress EGFR (IC50 1 mmol/L for A431 cells) and growth of A431 cells (human epithelial carcinomas) in a nude mouse xenograft model." (PMID 23586056, 2013). "For CRC, the most popular tumor derived cell lines, carefully analyzed for the expression of EGFR and chemotherapy response towards treatment with a typical immunotoxin, are represented by HT-29, HCT-116, SW-620, COLO205 and others." (PMID 23857061, 2013). "In contrast, EGFR/HER1 expression levels correlated negatively with ESR1 tumour levels (r=-0.629, P=0.012) in addition to intratumour (r=-0.633, P=0.001), normal tissue (r=-0.556, P=0.005) and plasma (r=-0.625, P=0.002) E2 levels." (PMID 23991224, 2013). "Tumor differentiation, CXCR1/2, pAKT, Ki-67 and EGFR expression were associated with high T stage by the multivariate analysis." (PMID 23420470, 2013). "The epidermal growth factor receptor (EGFR)-RAS-RAF signaling pathway plays an important role in regulation of tumor cell survival and proliferation." (PMID 23637996, 2013). "EGFR immunoexpression correlated significantly with tumour grade, being more often positive in high and moderately differentiated tumours." (PMID 24204699, 2013). "Earlier studies have reported the high tumor-specific uptake and good tumor-to-background ratio of the ZEGFR:1907 affibody in EGFR-expressing A431 tumor xenografts using optical and PET imaging modalities." (PMID 23710458, 2013).
tumor (continued). "HER3 expression correlated positively to HER2 (r=0.532, P=0.009) as well as HER4 (r=0.480, P=0.020), but negatively to EGFR/HER1 (r=-0.450, P=0.031) in tumour tissue from postmenopausal patients." (PMID 23991224, 2013). "Within those models with EGFR and KRAS mutation, the anti-tumor efficacy of the EGFR tyrosine kinase inhibitor, gefitinib, was consistent with published preclinical data and clinical responses." (PMID 23842453, 2013). "To verify that rat stromal cells outgrew EGFR amplified tumor cells from the three xenografts under different in vitro conditions, we used human- and rat-specific anti-nestin antibodies to detect and differentiate between cells from the different species." (PMID 24349039, 2013). "We report on three patients with metastatic SCC of the lung metastasizing to the gastrointestinal (GI) tract, two of whom had tumor with a confirmed EGFR exon 19 deletion." (PMID 24171005, 2013). "Although the objective response to erlotinib therapy was modest, the dominant component of the tumor in the present case changed from adenocarcinoma to SCLC after EGFR-TKI therapy." (PMID 24195468, 2013). "Mutations in EGFR and KRAS detected in tumors embedded in paraffin blocks and fresh-frozen tumor specimens appear to be mutually exclusive." (PMID 23817662, 2013). "GPR30 was predominantly expressed on plasma membranes and in cytoplasm, whereas EGFR was localized to plasma membranes in tumor tissues." (PMID 24289103, 2013). "When whole blood was used in the killing assay, IgA2 EGFR induced better tumour cell killing than cetuximab." (PMID 23918228, 2013). "COX-1, COX-2 and EGFR content in tumor and colon mucosa tissue were quantified by western blot and Q-PCR." (PMID 24171795, 2013). "EGFR, which has been identifies as one of factors to promote tumor cell proliferation was inhibited by berberine." (PMID 23457600, 2013). "The PCI treatment enhanced the cytotoxicity of the IT in a synergistic manner in EGFR-expressing carcinoma cell lines derived from different tumor tissues." (PMID 24105401, 2013). "Here we studied the in vivo anti-tumour activity of IgA EGFR antibodies generated using the variable sequences of the chimeric EGFR antibody cetuximab." (PMID 23918228, 2013). "GBM derived tumor initiating cells that express EGFR display the most malignant functional and molecular phenotype." (PMID 23637683, 2013). "The -216G/T genotypes were determined in all subjects by PCR amplification and direct DNA sequencing, and EGFR expression was also evaluated by immunohistochemical staining in the primary tumor tissues with various -216G/T genotype backgrounds." (PMID 24137392, 2013). "Regression analysis between COX-1 mRNA and EGFR mRNA showed a trend to significance in tumor tissue (p < 0.07)." (PMID 24171795, 2013). "This suggests that EGFR exon 19 deletions are present in the initial primary tumor clone that has metastatic potential." (PMID 24171005, 2013). "Both cisplatin and Epidermal Growth Factor Receptor (EGFR) antibodies like Cetuximab in combination with Radiotherapy (RT) are effective in enhancing tumour response." (PMID 23433435, 2013). "In our xenograft model, we clearly demonstrate that local delivery of an anti-EGFR antibody significantly inhibits tumor growth and invasion." (PMID 23429996, 2013). "In this model higher antibody concentrations were expected to reach the tumour environment, because EGFR antibodies were also injected intraperitoneally." (PMID 23918228, 2013). "In the clinical setting it has been demonstrated that ER+ tumours have lower levels of EGFR/HER1 protein than ER- tumours." (PMID 23991224, 2013). "The in vitro data suggest that EGFR and Rictor dual suppression increased tumor cell sensitivity to temozolomide, irinotecan and vincristine; drugs which have been proven to prolong the survival time of GBM patients." (PMID 23555046, 2013).
tumor (continued). "The health authorities regulatory restriction of the prescription of anti-EGFR monoclonal antibodies to wild-type KRAS tumor patients plays a major role in selecting anti-VEGF or anti-EGFR introduction in first-line therapy." (PMID 24133623, 2013). "Microdissection yielded 1,431 tumor foci from EGFR mutant patients (group-M) and 1,238 foci from wild-type patients (group-W)." (PMID 23418425, 2013). "Based on this observation, we analyzed the xenograft for EGFR expression by flow cytometry and found a low level of EGFR expression on the tumor cells." (PMID 24260133, 2013). "This is due to the fact that HGF can transactivate EGFR and phosphorylation of EGFR can activate c-Met resulting in synergistic effects on tumor growth." (PMID 24223799, 2013). "Soluble tumor-cell-derived factors trigger mononuclear cells to co-secrete lineage-specific EGFR agonists together with a common STAT3 activator." (PMID 23597096, 2013). "Tumor characteristics, including KRAS mutation status as well as EGFR expression and phosphorylation levels, have been reported previously." (PMID 23935914, 2013). "At the end of the experiment, tumor volume was calculated, and tumors were weighed, and examined for EGFR expression, proliferation, and apoptosis evaluations." (PMID 27234384, 2013). "The studies that established the relationship between mutations in the EGFR gene and response to the small molecule EGFR TKIs gefitinib and erlotinib were done using analysis of DNA extracted from the tumor." (PMID 23419122, 2013). "In the first 4 days the mice were treated intraperitoneally with 50 μg IgA2 EGFR daily, and tumour growth was followed by serial BLI." (PMID 23918228, 2013). "p140CAP arrests E-cadherin at the cell membrane and prevents EGFR and Erk1/2 signaling, decreasing proliferation of tumor cells." (PMID 23469205, 2013). "Nowadays, multiple therapeutic targets have been made against EGFR to treat this tumor, but success is still far behind." (PMID 23675485, 2013). "Cells with high EGFR amplification are more frequent in invasive areas as compared to the main angiogenic tumor mass." (PMID 23429996, 2013). "The multivariate analysis further showed that histological grade, positive lymph nodes, tumor size and EGFR expression were independent prognostic factors for OS and DFS of these patients." (PMID 24131756, 2013). "Using this approach, exosomes displaying the GE11 peptide, which targets epidermal growth factor (EGFR), accumulated in EGFR+ human xenograft tumor models in mice to levels three times higher than those observed using non-targeted exosomes." (PMID 23894228, 2013). "In 38 cases (2.7%) where we were unable to detect an EGFR alteration, the content of tumor cells in the sample was considered too low to conclude." (PMID 23934203, 2013). "In the present study, nimotuzumab inhibited tumor cell proliferation in vitro via an EGFR-dependent signaling transduction mechanism." (PMID 23496982, 2013). "The immunohistochemical assay showed that the expression of CD3 in the tumor tissues of the mice treated with the EGFR/CD3 BsAb-redirected CIK cells was increased significantly and the positive signals were mainly distributed in the membrane and cytoplasm." (PMID 23833649, 2013). "Over-expressed or activated EGFR signaling is the initial step of a cascade of events leading to tumor cell proliferation, invasion, migration and evasion of apoptosis." (PMID 24314030, 2013). "In the past years several studies have pointed to the importance of EGFR and NF-kB pathways in formation, growth and relapse of many tumor types, including GBM, and recent evidence suggests a cross-talk between these pathways." (PMID 24330732, 2013). "Truncated mutant EGFR variant III expression, in which exons 2–7 are deleted, was detected in 42% of HNSCC tumors, resulting in constitutive activation of EGFR, increased proliferation and tumor volume, and enhanced resistance to targeting wild-type EGFR." (PMID 24970177, 2013).